FGF21 (fibroblast growth factor 21)
Diseases named in the same sentence as FGF21 in open-access papers (continued):
Sharing a sentence is not in itself a finding about the gene and the disease.
migraine (4 papers, 2021 to 2025). "Serum GDF-15 and FGF-21 levels are increased in patients with migraine and associated with the severity of migraine-related disability." (PMID 36935492, 2023). "The heightened concentrations of GDF-15 and FGF-21 are linked to greater disease burden, indicating their potential as peripheral blood markers for evaluating the severity of migraine-related disability." (PMID 36935492, 2023). "The associations between the clinical variables of migraine patients and serum levels of FGF-21 and GDF-15 were studied." (PMID 36935492, 2023). "This study investigated whether the presence of migraine affects serum levels of FGF-21 and GDF-15, both of which have been implicated in metabolic disorders." (PMID 36935492, 2023). "For serum FGF-21, the AUC in predicting migraine, EM, CM in all subjects for FGF-21 was 0.729 (sensitivity 59.70%; specificity 87.93%), 0.755 (sensitivity 59.06%, specificity 86.29%), 0.755 (sensitivity 65.79%; specificity 85.60%), respectively." (PMID 36935492, 2023). "Regarding migraine-related disability, higher scores on the HIT-6 and MIDAS were associated with higher levels of FGF-21 and GDF-15." (PMID 36935492, 2023). "Our research found a positive correlation between age and the concentrations of GDF-15 and FGF-21 not only in the migraine group but also in the healthy group." (PMID 36935492, 2023). "The elevated levels of GDF-15 and FGF-21 in patients with migraine are insufficient to support the potential mechanism of mitochondria in migraine." (PMID 36935492, 2023). "This study investigated the association between serum concentrations of the biomarkers FGF-21 and GDF-15, which have been investigated for mitochondrial diseases, and the presence of migraine." (PMID 34572118, 2021). "We have demonstrated that serum levels of GDF-15 and FGF-21 are elevated in patients with migraine." (PMID 36935492, 2023). "This study aimed to assess whether the presence of migraine affects serum levels of FGF-21 and GDF-15, and taking metabolic disorders into account as potential confounding factors." (PMID 36935492, 2023). "The study investigated whether the presence of migraine may influence FGF-21 and GDF-15 serum levels considering vascular and metabolic disorders as possible confounders." (PMID 34572118, 2021). "Migraine attacks were recently shown to be accompanied by elevated HIF-1α, FGF-21, GDF-15, CGRP, and PACAP-38 in medication-naïve children with migraine." (PMID 38369488, 2024). "Serum levels of both FGF-21 and GDF-15 in migraine patients were significantly higher than that in healthy controls (p < 0.001)." (PMID 36935492, 2023). "We calculated the area under the receiver operating characteristic (ROC) curve to evaluate the effectiveness of FGF-21 and GDF-15 prediction model for patients with migraine." (PMID 36935492, 2023). "In the multiple regression that corrected for age, we found that the serum levels of FGF-21 and GDF-15 were significantly higher in migraine sufferers than in healthy controls." (PMID 36935492, 2023). "The higher concentrations of serum FGF-21 and GDF-15 observed in individuals with migraine and increased burden and disability suggest a potential correlation between disease severity." (PMID 36935492, 2023). "The study found significantly heightened serum levels of FGF-21 and GDF-15 in patients with migraine compared to a control group, which suggests that both cytokines may have potential value in distinguishing between migraine sufferers and healthy controls." (PMID 36935492, 2023). "The question of whether the levels of FGF-21 and GDF-15 can serve as a reference for the personalized use of nutraceuticals in the treatment of migraine is a topic that merits further investigation." (PMID 36935492, 2023). "It remains elusive for the role of FGF-21 and GDF-15 in migraine." (PMID 36935492, 2023).
migraine (continued). "Hence, in this study, we analyzed serum concentrations of FGF-21 and GDF-15 in patients with migraine and healthy controls and the relationship of these cytokines with patients’ clinical parameters." (PMID 36935492, 2023). "Additionally, among the migraine group, higher concentrations of FGF-21 and GDF-15 were significantly correlated with increased migraine-related burden and disability, as evidenced by higher scores on the HIT-6 and MIDAS assessments." (PMID 36935492, 2023). "This study investigated whether serum concentrations of both FGF-21 and GDF-15 are altered in patients suffering migraine considering disease severity, attack morphology and concomitant disorders." (PMID 34572118, 2021). "Further studies, preferably in a younger group, could investigate the effect of vitamin B2 (riboflavin) and coenzyme Q 10 in migraine patients with elevated GDF-15 and/or FGF-21 levels." (PMID 34572118, 2021). "In a non-parametric analysis, elevated serum levels of GDF-15, but not FGF-21, were found in a large cohort of patients with migraine compared with an appropriately sized control group." (PMID 34572118, 2021). "The plasma level of FGF-21 was not different comparing the migraine group (27.5 pg/mL, 16.3–85.5 pg/mL, n = 230) with the control group (38.0 pg/mL, 14.9–94.0 pg/mL, n = 98, p = 0.635, Mann–Whitney U test)." (PMID 34572118, 2021).
muscular dystrophy (4 papers, 2019 to 2024). Muscular dystrophy (MD) refers to a group of more than 30 genetic diseases characterized by progressive weakness and degeneration of the skeletal muscles that control movement. "Similarily, increased serum FGF21 and decreased FGF21 in the liver and is also observed in mice with muscular dystrophy." (PMID 39066929, 2024). "Under basal conditions, the expression of FGF21 is predominantly from liver and adipose tissue, however, the expression and secretion of FGF21 from skeletal muscle is significantly increased under certain conditions, such as mitochondrial dysfunction, muscular dystrophy, and exercise." (PMID 33762965, 2021).
sleep disorder (4 papers, 2020 to 2025). A change from the patient's baseline sleeping pattern, in the hours slept and/or an alteration/dysfunction in the stages of sleep. "In regard to the relationship between the FGF-21 concentrations and sleep disorders, we found three studies." (PMID 41010737, 2025). "Clarification of hypoxia-regulated FGF21 regulation will enhance our understanding of the pathophysiology of hypoxia-related diseases, such as sleep disorders and metabolic diseases." (PMID 32922298, 2020). "Higher FGF-21 levels were observed among airline pilots with sleep disturbances." (PMID 41010737, 2025). "Interestingly, we recently reported that post-menopausal women suffering by chronic insomnia, a condition known to be a risk factor for the development of AD, display lower levels of FGF21 as compared with age-matched women without sleep disorders." (PMID 33131010, 2021). "We found a significant difference in the circulating levels of FGF21 and HN, but not GDF15, between patients and age-matched women without sleep disorders, who were enrolled in a previous study conducted in our laboratory." (PMID 32420904, 2020).
unstable angina pectoris (4 papers, 2018 to 2025). "By comparing serum FGF21 concentrations in patients with unstable angina pectoris with those in patients with stable angina pectoris, it was found that unstable angina pectoris was significantly higher than stable angina pectoris patients and healthy controls." (PMID 40076419, 2025). "In another study, it was shown that patients with unstable angina pectoris had greater levels of serum FGF21 compared to the case and control groups." (PMID 38333506, 2024). "Circulating FGF21 level was examined in 197 patients with stable angina pectoris (SAP, n=66), unstable angina pectoris (UAP, n=76), and control subjects (n=55) along with clinical variables of cardiovascular risk factors." (PMID 30185439, 2018).
alcohol use disorder (3 papers, 2022 to 2025). "Further, FGF21 is implicated in the genetics of alcohol intake and alcohol-use disorder." (PMID 40604130, 2025).
alcoholic cirrhosis (3 papers, 2016 to 2022). "To better understand the relation of FGF21 and alcohol intake in humans, we measured FGF21 levels in patients with alcoholic liver cirrhosis (ALC), in patients with nonalcoholic liver cirrhosis (NALC) and healthy persons to correlate their present alcohol consumption." (PMID 33330965, 2021). "Significantly higher FGF21 levels with positive ETG levels are seen in our study compared to those with negative ETG levels applying to the group of alcoholic liver cirrhosis and nonalcoholic liver cirrhosis." (PMID 33330965, 2021). "However, circulating FGF21 is not a biomarker of liver damage in patients with alcoholic cirrhosis." (PMID 35369322, 2022).
Anorexia (3 papers, 2011 to 2021). Lack of desire to eat (loss of appetite). "We have previously shown that Ay mutation exaggerated stress anorexia in male mice, and our results suggest that FGF21 counteracts stress-induced anorexia in Ay mice." (PMID 34943946, 2021). "Additional studies are needed to elucidate the regulation and role of FGF21 in anorexia patients." (PMID 21829679, 2011). "Moreover, recent data demonstrated that mitochondrial stress-induced GDF15 promotes a day-time restricted anorexia and systemic metabolic remodeling as shown in UCP1-transgenic mice, where both FGF21 and GDF15 are induced as myomitokines." (PMID 33464381, 2021).
Arrhythmia (3 papers, 2021 to 2023). Any cardiac rhythm other than the normal sinus rhythm. "FGF21 has been shown to improve post-infarction arrhythmias and preserve electrophysiological function through mediating cardiac sodium current and inward rectifier potassium current." (PMID 37416922, 2023). "To shed light on this issue, we explored the effect of FGF21 on the ion pathways of myocardial cells after MI and discovered the mechanism of preventing arrhythmia after MI by affecting the ion pathways." (PMID 34630093, 2021). "In order to clarify the regulation of FGF21 on arrhythmia, two kinds of arrhythmia animal models were established in our study, including ischemic arrhythmia model (MI rat model) and nonischemic arrhythmia model (ouabain-induced guinea pig arrhythmia model)." (PMID 34630093, 2021). "In order to clarify the regulation of FGF21 on arrhythmia, two kinds of arrhythmia animal models were established in this study, including ischemic arrhythmia model (MI rat model) and nonischemic arrhythmia model (ouabain-induced guinea pig arrhythmia model)." (PMID 34630093, 2021). "For atrial remodeling induced by oxidative stress, FGF21 functioned by regulating the degradation of myofibrils and levels of calpain, a calcium-dependent protease, which helped to maintain cardiac function, improved arrhythmia symptoms, and preserved electrophysiological function." (PMID 37416922, 2023). "Therefore, we hypothesized that the protective effect of FGF21 on arrhythmia may be related to maintaining the functional balance of ion channels or stabilizing the myocardial cell membrane." (PMID 34630093, 2021). "We used ouabain-induced arrhythmia of the guinea pig model, a classic nonischemic arrhythmia model, to further explore the regulatory effect of FGF21 on arrhythmia." (PMID 34630093, 2021). "Yet, the role of FGF21 in cardiac arrhythmia has never been studied." (PMID 36180826, 2022). "Secondly, we used ouabain-induced arrhythmia of the guinea pig model, a classic nonischemic arrhythmia model, to further explore whether FGF21 has a regulatory effect on malignant ventricular arrhythmia and sudden cardiac death." (PMID 34630093, 2021). "Collectively, FGF21 has the potential role of ameliorating transmembrane ion channels remodeling through the NaV1.5/Kir2.1 pathway by FGF receptors and thus reducing life-threatening postinfarcted arrhythmias, which provides new strategies for antiarrhythmic therapy in clinics." (PMID 34630093, 2021).
Arthritis (3 papers, 2016 to 2020). Inflammation of a joint. "In the report of Yu, FGF21 ameliorates collagen-induced arthritis through modulating oxidative stress and suppressing NF-κB pathway." (PMID 27274736, 2016). "Importantly and related to arthritis, FGF-21 was found to attenuate the collagen-induced arthritis by reducing, among other things, some pro-inflammatory cytokines." (PMID 32012117, 2020).
asthma (3 papers, 2023 to 2025). "Serum LCN2, sST2, and FGF21 levels increase with asthma severity and demonstrate high predictive value for poor prognosis when combined." (PMID 41230779, 2025). "This study aimed to investigate the association between serum levels of lipocalin-2 (LCN2), soluble suppression of tumorigenicity 2 (sST2), and fibroblast growth factor 21 (FGF21) with asthma severity and to evaluate their predictive value for prognosis." (PMID 41230779, 2025). "FGF19 had a negative association with asthma among overweight/obese subjects whereas FGF21 had a positive association." (PMID 36973952, 2023). "Furthermore, FGF21 is a marker that can distinguish controlled from poorly controlled asthma, which is in line with our findings in PW‐R being in remission." (PMID 38006384, 2023).
autoimmune disease (3 papers, 2023 to 2025). A disorder resulting from loss of function or tissue destruction of an organ or multiple organs, arising from humoral or cellular immune responses of the individual to their own tissue constituents. "In this case, we believe the combined effect of an intense inflammatory response (characteristic of autoimmune diseases) and the activation of metabolic pathways related to FGF21 is responsible." (PMID 39941067, 2025).
colon cancer (3 papers, 2021 to 2023). "Interestingly, when stratifying by anatomical tumor sub-site, it became evident that the association between FGF-21 and colon cancer was driving this association." (PMID 33664295, 2021). "FGF-21 remained associated with colon cancer after adjusting for BMI, education and smoking." (PMID 33664295, 2021).
dementia (3 papers, 2022 to 2025). Loss of intellectual abilities interfering with an individual's social and occupational functions. "Findings from this study suggested that the effects of exercise on BDNF, irisin, IGF-1, and FGF-21 may be heterogeneous in older adults with mild-to-moderate AD dementia." (PMID 39328309, 2023). "Other blood biomarkers that could be elevated in the preclinical stage of dementia, such as insulin, fibroblast growth factor 21, lipocalin-2, or trimethylamine N-oxide may need to be considered to help increase the discriminative properties." (PMID 36292406, 2022).
Duchenne muscular dystrophy (3 papers, 2021 to 2026). Duchenne muscular dystrophy (DMD) is a neuromuscular disease characterized by rapidly progressive muscle weakness and wasting due to degeneration of skeletal, smooth and cardiac muscle. "have described that the expression of FGF21 is increased in muscles of mdx mice, a model of Duchenne muscular dystrophy." (PMID 36909316, 2023). "In a Duchenne muscular dystrophy (DMD) mouse model, FGF-21 exerts a direct positive influence on RANKL-induced osteoclastogenesis, which causes increased bone resorption." (PMID 41495343, 2026).
Encephalopathy (3 papers, 2018 to 2025). Encephalopathy is a term that means brain disease, damage, or malfunction. "This research, therefore, seeks to primarily elucidate the effect of FGF21 on encephalopathy with ALF as the precipitating factor." (PMID 32483404, 2020). "FGF21 downregulated the expression of both TGF-β1 and Col1, resulting in the amelioration of the encephalopathy." (PMID 32483404, 2020). "A weak correlation was found between FGF-21 concentrations and the severity of myopathy and between FGF-21 concentrations and the severity of the encephalopathy." (PMID 29385732, 2018).
endometrial cancer (3 papers, 2020 to 2025). Primary or metastatic malignant neoplasm involving the endometrium (mucous membrane that lines the endometrial cavity). "Having applied multivariate logistic regression analysis for the risk of the development of endometrial cancer, in the final model, independent risk factors were found: BMI, FGF21, and leptin level." (PMID 32570721, 2020). "Serum FGF21 and LEP concentrations are increased in patients with endometrial cancer, and associated with low differentiation and higher grade of tumor." (PMID 34068954, 2021). "FGF21 and FGF23 expression have been implicated in endometrial cancer due to their association with increased expression of leptin (LEP), a hormone produced in adipose tissue." (PMID 34068954, 2021). "The median of FGF21 protein (181.8 pg/mL) as well as leptin (16.9 ng/mL) in patients with endometrial cancer was statistically significant higher compared to median of those proteins among patients from control group (152.1 pg/mL and 14.1 ng/mL, respectively)." (PMID 32570721, 2020). "In our studies, we were able not only to observe higher serum levels of leptin and FGF21 in endometrial cancer patients but also to confirm the correlation of FGF21 levels with cancer stage and grade in these patients." (PMID 32570721, 2020). "We also found differences in the median concentrations of both FGF21 and leptin in patients with endometrial cancer compared to those in the median concentration in the group of patients with endometrial polyps." (PMID 32570721, 2020). "Importantly, serum levels of FGF21 were higher not only in patients with advanced endometrial cancer but also in patients with early stages of the disease." (PMID 32570721, 2020). "In our study we assessed role of FGF21 and FGF23 in the diagnostics of patients with endometrial cancer." (PMID 32570721, 2020). "Considering the currently negative prognostic factors of endometrial cancer, statistically significant differences between endometrial vs. non-endometrial types have been demonstrated only in relation to FGF-21 protein." (PMID 32570721, 2020). "Similarly, studies on FGF21 in patients with type II endometrium and slim patients in older age seem to confirm that FGF acts as an independent factor in endometrial cancer, via FGFR 2 and the PI3K/Akt, mTOR signaling pathways." (PMID 32570721, 2020). "In our study, we observed significantly higher levels of leptin and FGF21, but not of FGF23, in overweight and obese patients with endometrial cancer." (PMID 32570721, 2020).
energy metabolic disorders (3 papers, 2018 to 2025). "As a neuroprotective agent, FGF21 attenuated neural cell apoptosis, oxidative stress, and mitochondrial energy metabolism disorder." (PMID 40581646, 2025). "Future research could focus on the role of FGF21 in energy metabolic disorders in perinatal dairy cows, and lay a theoretical basis for exploring new targets and approaches for the prevention and treatment of energy metabolic disorders in dairy cows." (PMID 35405926, 2022). "In addition to our interest in whether ANGPTL4 and FGF21 participate in the pathological process of energy metabolic disorders in cows, we hypothesized that the serum concentration of these two hepatokines in dairy cows with ketosis and fatty liver are different from the contemporary healthy cows." (PMID 30103741, 2018). "Although FGF21 and ANGPTL4 could play important roles in the adaptation of energy metabolism, they may be involved in the pathological processes of energy metabolism disorders of dairy cows in the peripartum period." (PMID 30103741, 2018). "Although FGF21 and ANGPTL4 have important roles in the adaptation of energy metabolism, these two hepatokines may be involved in the pathological processes of energy metabolism disorders during the peripartum period in dairy cows." (PMID 30103741, 2018). "According to our results, we speculate that upregulation of FGF21 and ANGPTL4 due to NEB could diminish adipose tissue insulin sensitivity and further aggravate lipolysis during early lactation in dairy cows, thus playing a role in the pathological processes of energy metabolism disorders." (PMID 30103741, 2018).